MITF (melanocyte inducing transcription factor)
Diseases named in the same sentence as MITF in open-access papers (continued):
Sharing a sentence is not in itself a finding about the gene and the disease.
melanoma (continued). "The stimulation of melanoma cells with interleukin-1α or 1β resulted in the reduction of MITF expression, and it has been suggested that this process is NF-κB-dependent." (PMID 25433395, 2015). "There is therefore no general requirement for BPTF for proliferation, but rather a specific requirement in melanoma cells that is both MITF-dependent and independent." (PMID 26440048, 2015). "Using these criteria, the rheostat model suggests that melanoma cells – depending on their MITF activity level – are either proliferating or invading." (PMID 25818589, 2015). "High MITF activity induces terminal melanocyte differentiation and can also induce cell cycle arrest of melanoma cells." (PMID 26440048, 2015). "The level of functional MITF expression determines many of the proliferation and invasion properties of melanoma cells and siRNA-mediated MITF silencing induces senescence in several melanoma lines." (PMID 25803486, 2015). "A couple of other transcriptional regulators of MITF expression have been identified, where follow‐up studies in human melanoma are missing." (PMID 25818589, 2015). "The chemotherapeutic agent methotrexate (MTX) causes an increase in MITF and its direct target TYR (tyrosinase) that inhibit invasiveness in melanoma." (PMID 25763355, 2015). "By activating the expression of almost one hundred genes, MITF can regulate multiple biological processes in melanoma cells such as differentiation, proliferation, migration, and senescence [11–13; for review 14, 15]." (PMID 25433395, 2015). "In the present study, we focused on the melanogenic activity of cirsimaritin and its molecular mechanisms, and found that cirsimaritin upregulates melanin synthesis through cAMP/PKA-dependent CREB activation and MITF upregulation in melanoma cells." (PMID 25903150, 2015). "Next, we asked how inflammatory TNF-α signalling interconnects with the identified MITF/c-Jun antagonism in melanoma cells." (PMID 26530832, 2015). "Particularly, by decoding the sequences of the differentially active regulatory regions, we identified SOX10 and MITF as master regulators of the melanoma-proliferative cell state." (PMID 25865119, 2015). "This review aims to provide an updated overview on the regulation of MITF function and plasticity in melanoma with a focus on its link to MAPK signaling." (PMID 25818589, 2015). "Although positive regulation of MITF by PAX3 in melanocytes is well described, PAX3 is thought to function independently of MITF or even play a repressive role on MITF expression in melanoma." (PMID 25433395, 2015). "In agreement, CITED1 positively correlates with MITF expression and can discriminate the MITF-high/pigmentation tumour molecular subtype in a large cohort of melanoma cell lines." (PMID 25755924, 2015). "Our findings suggest that MITF directly suppresses c-Jun through binding in its regulatory enhancer region and thereby negatively controls priming of inflammatory pathways in melanoma cells." (PMID 26530832, 2015). "At the molecular level, epigenetic mechanisms and variable activity of microphthalmia-associated transcription factor (MITF) have been associated with interconversions of melanoma cell phenotypes." (PMID 26035829, 2015). "It has been demonstrated that MITF-mediated downregulation of Dia1 (diaphanous-related protein) triggers actin re-organization, thereby leading to increased melanoma cell invasion." (PMID 26393652, 2015). "On the other hand, ectopic overexpression of β‐catenin stimulates melanoma cell growth in a MITF‐dependent manner, suggesting an altered transcriptional activity of β‐catenin in the absence of a Wnt3 signalling context." (PMID 25818589, 2015). "MITF targets are up-regulated by MAPK-pathway inhibitors, and enforced expression of MITF in BRAFV600E melanoma cells promotes resistance towards inhibitors of RAF, MEK and ERK [for review 134]." (PMID 25433395, 2015).
melanoma (continued). "This, however, is not an exclusive role of the BRG1-containing SWI/SNF complex in melanoma since its MITF-independent activity has been shown as well." (PMID 25433395, 2015). "Expression of MITF in melanoma is variable and is driven by a number of factors including LEF/β-catenin and SOX10 in conjunction with CREB (cyclic AMP response element binding protein), a cyclic AMP responsive cofactor." (PMID 26426052, 2015). "Clear cell sarcoma (CCS), initially named malignant melanoma of soft parts, is an aggressive soft tissue sarcoma (STS) that, due to MITF activation, shares with melanoma the expression of melanocyte differentiation antigens." (PMID 25880253, 2015). "In another study, an inverse association was observed between MITF, Vemurafenib resistance and EGFR in tumor specimen and in melanoma cell lines." (PMID 26393652, 2015). "As a ‘master regulator’ of melanoma cell biology, MITF's most important role is probably its function in proliferation and survival, which also explains why MITF expression is maintained throughout tumour progression." (PMID 25818589, 2015). "Microphthalmia-associated transcription factor, MITF, acts as a master-regulator of melanocyte differentiation and as a result has been intensely studied in the field of melanoma research (Widlund & Fisher, 2003; Levy, Khaled & Fisher, 2006)." (PMID 25755924, 2015). "In line with this, BRN2 increases transcription from the MITF promoter in a panel of BRAF mutant melanoma cells." (PMID 25818589, 2015). "Between these two extremes however it is thought that melanoma cells can oscillate from a low-MITF ‘invasive’ to a high-MITF ‘proliferative’ state via phenotype-switching." (PMID 25755924, 2015). "In melanoma, MITF expression is mostly heterogeneous, and immunohistological staining identifies ‘MITF‐positive’ cells expressing higher and lower levels of MITF, but also cells that lack MITF expression entirely." (PMID 25818589, 2015). "A comprehensive analysis of the MITF ‘interactome’ in 501Mel melanoma cells revealed that the NURF (Nucleosome Remodelling Factor) complex associates with MITF." (PMID 26440048, 2015). "These and other observations gave rise to the proposed ‘rheostat’ model postulating that the level of functional MITF expression determines many biological properties of melanocytes and melanoma cells." (PMID 26440048, 2015). "Co‐operativity also agrees with the heterogeneity of MITF expression detected in circulating melanoma cell clusters." (PMID 25818589, 2015). "For instance, a reversible switch between populations of undifferentiated and differentiated MITF‐positive cells can be observed during melanoma progression." (PMID 25818589, 2015). "It has also been shown that BRAF triggers MITF expression in melanoma cells by inhibiting Brn-2, a transcription factor." (PMID 26393652, 2015). "It has been proposed that TRPM1 expression in melanocytes and melanoma cells is regulated by a promoter region of the gene that contains four microphthalmia transcription factor (MITF) binding sites." (PMID 25710007, 2015). "Nevertheless, MITF is a potent regulator of melanoma lineage and to a large extent determines the basal transcriptional profile, hence its association with the first Principal Component of our basal transcriptional analysis." (PMID 26405815, 2015). "A few natural compounds that either reduced or increased MITF transcript level in heterogeneous patient-derived melanoma populations were identified in our laboratory." (PMID 25433395, 2015). "Apart from its effect on melanoma progression, MITF heterogeneity also will impact on MAPK pathway targeted therapy." (PMID 25818589, 2015). "Depletion of MITF from high or low MITF‐expressing cells results in a G1 arrest, demonstrating that it is essential for driving melanoma cell proliferation independently of its expression level." (PMID 25818589, 2015).
melanoma (continued). "MITF is a lineage commitment factor essential for propagation of the melanocyte lineage in early development, and importantly, this role is maintained in melanoma cells." (PMID 25818589, 2015). "Here we identify an antagonism between MITF and c-Jun as a molecular interface between pro-inflammatory signals from the tumour microenvironment and melanoma cell plasticity." (PMID 26530832, 2015). "We confirmed this heterogeneity by immunoblotting in time-course experiments showing that MITF loss and c-Jun accumulation after TNF-α treatment are tightly coordinated events in melanoma cells." (PMID 26530832, 2015). "MITF operates within a wide range of activity levels determining melanoma cell fate [20, 24–27; for review 22, 23, 28]." (PMID 25433395, 2015). "The interaction of MITF with NURF prompted us to investigate its role in melanoma cells and in the melanocyte lineage." (PMID 26440048, 2015). "MITF is also recognized as a major regulator in a “phenotypic switching” concept explaining a high plasticity of melanoma cells [20, 21, 24–27; for review 22, 28]." (PMID 25433395, 2015). "Transcription factor MITF acts as a rheostat determining the phenotypic identity among different subpopulations of melanoma cells." (PMID 24595456, 2014). "MITF expression and, as a consequence, PGC1a levels, are upregulated in melanoma lines and in tumors of patients treated with Vemurafenib." (PMID 24743024, 2014). "The findings gathered in this study not only contribute to better understand the role of MITF in melanoma cells but also provide strong support that targeting SIRT1 is a valuable clinical option to treat malignant melanoma." (PMID 24742694, 2014). "One of the major determinants of melanoma heterogeneity is the regulation of MITF expression by the tumor microenvironment." (PMID 25066122, 2014). "MITF is considered to be the central transcription factor regulating melanoma phenotypic plasticity, and it was reported that MITF expression better correlates with the expression of its targets than the MITF copy number." (PMID 24733089, 2014). "In melanoma, the induction of MITF expression promotes expression of differentiation markers and the inhibition of invasion." (PMID 25051363, 2014). "We have previously shown that melanoma cell cultures contained a low-MITF population endowed with MIC properties." (PMID 25105565, 2014). "SIRT1 over-expression relieves the senescence-like phenotype and the proliferation arrest caused by MITF suppression, demonstrating that SIRT1 is an effector of MITF-induced proliferation in melanoma cells." (PMID 24742694, 2014). "Another study showed that high MITF expression protected melanoma cells against MEK inhibitor cytotoxicity." (PMID 24733089, 2014). "MITF is a lineage-specific oncogene that is frequently amplified or overexpressed in human melanomas." (PMID 25538895, 2014). "Although amplified only in about 20% of melanomas, MITF has been proposed as a lineage addiction oncogene contributing to melanoma chemoresistance." (PMID 24595456, 2014). "The role of MITF in melanoma is controversial, as MITF levels are subjected to a tight regulation and different levels of MITF exert different effects in melanomagenesis." (PMID 25538895, 2014). "SIRT1 forced expression, led to an increased SIRT1 activity, and prevented SA-βGal staining mediated by MITF-suppression in melanoma cells." (PMID 24742694, 2014). "Among the down-regulated genes, we found MITF which controls proliferation and invasiveness of melanoma cells and the endothelin receptor b (EDNRB) which is strongly associated with melanoma development and central nervous system directed metastasis." (PMID 24799129, 2014). "A decrease in expression of the melanoma differentiation antigens (MDA) under the control of MITF during EMT has also been reported by others, e.g., gp100." (PMID 25566505, 2014).
melanoma (continued). "The mutual expression of Axl and N-cadherin in a heterogeneous melanoma cell population also marks a more invasive phenotype, compared to expression of MITF and E-cadherin." (PMID 25344858, 2014). "BCL2A1, a lineage-specific anti-apoptotic protein in the BCL2 family, is amplified and overexpressed in MITF-high melanomas, and confers resistance to BRAF inhibitor." (PMID 24743024, 2014). "SOX10 is known to act as a specifier of neural crest derivatives and directly regulates melanoma associated genes like ERBB3, EDNRB and MITF." (PMID 24799129, 2014). "TGF-β is critical in the regulation of Gli2, which in turns has antagonistic effect on MITF expression, eventually leading to melanoma invasion and metastasis." (PMID 25538895, 2014). "Expression of MITF has also been reported to be reduced in mammalian melanocytes exposed to 4-tert-butylphenol or melanoma cells exposed to hydrogen peroxide." (PMID 25402455, 2014). "Further, depletion of the low-MITF population, which is a slow growing population, impairs severely the tumorigenicity of melanoma cells." (PMID 25105565, 2014). "In conclusion, our results indicate that SIRT1 acts downstream of MITF in the regulation of melanoma cell proliferation." (PMID 24742694, 2014). "Inhibition of BRAF leads to inhibition of glycolytic pathway for ATP production, but MITF-expressing melanomas can undergo a bioenergetics adaptation via MITF-PGC1a-OXPHOS upregulation." (PMID 24743024, 2014). "Considering that MITF itself is currently not a druggable target, inhibition of CDK2 is a plausible aim in melanoma with MITF aberrations." (PMID 24743024, 2014). "The crystal structure of MITF was resolved recently, paving the way for the future targeting of MITF in melanoma and other cancers." (PMID 24743024, 2014). "The M-isoform of MITF is specifically expressed in melanocytes and nearly all melanoma cells express MITF." (PMID 24742694, 2014). "As MITF has been shown both in vitro and in vivo to be critical to melanoma cell proliferation/survival, A375 or 1205Lu cells with very low level of MITF have likely adapted to the lost of MITF." (PMID 24742694, 2014). "β-catenin suppresses invasion through a cell-type specific mechanism involving MITF, and, interestingly, MITF overexpression in invasive colon cancer cells induces a “melanoma phenotype”." (PMID 24733089, 2014). "After methotrexate-mediated upregulation of MITF in melanoma cells, tyrosinase expression was induced." (PMID 25538895, 2014). "Our results show that SIRT1 over-expression rescued melanoma proliferation arrest mediated by MITF knock-down, thereby indicating that SIRT1 is an effector of MITF-induced cellular proliferation." (PMID 24742694, 2014). "Paradoxically, expression of MITF itself is reduced under hypoxic conditions in normal melanocytes and melanoma via direct binding of transcription repressor DEC1, which is activated by HIF1α." (PMID 24743024, 2014). "BCL2A1 expression is apparently restricted to melanocytic lineage as it is indirectly controlled by MITF, and because of this its expression is limited to high-MITF-expressing melanomas." (PMID 24743024, 2014). "A recent paper proposed targeting of tyrosinase (MITF transcriptional target) by first inducing expression of MITF in melanoma cells using the well-known anti-folate drug methotrexate." (PMID 24743024, 2014). "qRT-PCR analysis showed expression of melanoma differentiation markers MLANA, TYR and MITF in the panel of 54 melanoma cell lines." (PMID 25051363, 2014). "In malignant melanomas this progeny is characterized by either the melanoma antigens HMB45 and MART-1, the microphthalmia-associated transcription factor (MITF) or the melanin synthesis controlling enzyme tyrosinase (TYR)." (PMID 24799129, 2014). "Nevertheless, BRM can also support MITF expression in 501mel cells if it is present as the only ATPase in melanoma cells." (PMID 23349796, 2013).
melanoma (continued). "MITF is considered a lineage addiction oncogene based on the ongoing requirement for MITF in melanoma tumorigenicity and contribution to melanoma chemoresistance." (PMID 23480510, 2013). "Here we demonstrate that survival of melanoma cells requires functional SWI/SNF complex not only by supporting expression of MITF and its targets and but also by activating expression of prosurvival proteins not directly regulated by MITF." (PMID 23349796, 2013). "Low levels of MITF expression have been shown to identify a small group of melanoma patients with high mortality." (PMID 24062982, 2013). "At the RNA level, there was good positive correlation between levels of CDK2 and the transcription factor MITF in both BRAF-V600E and NRAS mutated melanoma cell lines." (PMID 23527225, 2013). "This molecular reprogramming leads to an increase in the low-MITF and slow-growing cell population endowed with melanoma-initiating cell features." (PMID 24344100, 2013). "ML-IAP rescues melanoma viability in MITF-disrupted melanoma cells and can promote survival of malignant cells by intrinsic stress as well as in response to chemotherapeutics and other elicitors of DNA damage." (PMID 23480510, 2013). "MITF is a lineage addiction oncogene that is amplified in about 20% of melanomas and contributes to melanoma chemoresistance." (PMID 23480510, 2013). "Among the melanoma lines, we found that expression of MITF-M, the melanocyte-specific isoform of MITF, was positively related to that of E-cadherin but inversely related to that of N-cadherin and Axl." (PMID 23755070, 2013). "As has been comprehensively reviewed by several authors, MITF not only is the master regulator of healthy melanocytes, it also plays important roles in melanoma development." (PMID 24039954, 2013). "MITF immunostaining showed heterogeneity of expression in nevi and melanomas (score 0–3) with some cells being devoid of MITF expression, in concert with previous findings." (PMID 23349796, 2013). "MITF and P27 are the key molecules that switch the transition between melanoma-initiating cells and their differentiated progeny." (PMID 23762150, 2013). "We confirm this strong correlation in 10 of 11 tested melanoma cell lines, which clearly supports the idea that MITF drives expression of TRPM1 and by doing so it up-regulates miR-211, an intronic passenger of this gene." (PMID 24039954, 2013). "MITF is central for the transcription of genes involved in various cellular processes from embryonic development of melanocytes to metastasis of melanoma." (PMID 23349796, 2013). "It is possible that these “lower MITF” melanoma cell lines have an alternative pathway to suppress MITF that does not involve POU3F2 expression." (PMID 24062982, 2013). "Proper identification can be attained through use of MART-1 and MITF melanoma stains, and via FISH to detect EWS gene rearrangement." (PMID 24274261, 2013). "In this study, we determined that BRG1 protects melanoma cells from apoptosis following UV irradiation by cooperating with MITF to regulate ML-IAP transcription." (PMID 23480510, 2013). "In contrast, in melanoma cells in vivo where the MITF expression is high there is likely to be a minimal role of the PAX3-POU3F2 axis in promoting melanoma cell invasion." (PMID 24062982, 2013). "In conclusion, here we have presented new evidence that PAX3 and MITF expression have independent and opposing effects in melanoma." (PMID 24062982, 2013). "This predicts that PAX3 and MITF play distinct roles in signaling pathways that promote melanoma progression, and also predicts additional features expected in melanoma cells undergoing phenotype switching." (PMID 24062982, 2013). "Microphthalmia-associated transcription factor (MITF) is a survival factor in melanocytes and melanoma cells." (PMID 23480510, 2013). "MITF activity can also influence melanocyte survival in response to UV radiation and melanoma resistance to chemotherapeutics." (PMID 23480510, 2013).